EGFR (epidermal growth factor receptor)
Diseases named in the same sentence as EGFR in open-access papers (continued):
Sharing a sentence is not in itself a finding about the gene and the disease.
colorectal cancer (continued). "Recently, in colorectal cancer (CRC) Cortactin overexpression has been correlated with inhibition of ubiquitin-mediated degradation of EFGR by suppressing the coupling of c-Cbl with EGFR." (PMID 30181811, 2018). "Anti-EGFR antibodies are used for the treatment of colorectal cancer." (PMID 29652830, 2018). "Also, several reports have shown the EGFR gene amplification in colorectal cancer (CRC) and squamous cell carcinoma of the head and neck (SCCHN), although EGFR mutations are less commonly detected." (PMID 30404198, 2018). "This is encouraging because Kras mutated NSCLC and colorectal cancers are non-responsive to EGFR TKIs or monoclonal antibody therapies." (PMID 30323890, 2018). "Monoclonal antibodies directed against the epidermal growth factor receptor (EGFR) are proven to be active anti-tumor agents in colorectal cancer (CRC) and squamous cell carcinoma of the head and neck (SCCHN), either alone or combined with chemo- and/or radiotherapy." (PMID 30557370, 2018). "EGFR mutation can also affect the sensitivity of colorectal cancers to gefitinib, but the effect is not consistent." (PMID 30187356, 2018). "For instance, in colorectal cancer, amplification of EGFR was associated with death even in tumors that lacked EGFR mutations." (PMID 30526857, 2018). "This could be of great interest in the treatment of peritoneal carcinomatosis of colorectal cancer origin in which EGFR upregulation has been demonstrated to be a factor of poor prognosis." (PMID 29777377, 2018). "However, EGFR remains a valid target in colorectal cancer within the population of patients wild-type for KRAS, NRAS, and BRAF, with proven clinical benefit." (PMID 29254887, 2018). "The anti-EGFR monoclonal antibody is approved for colorectal cancer without K-ras mutation, but the EXPAND trial confirmed the limited efficacy of cetuximab in first-line treatment of GC." (PMID 29433585, 2018). "These two properties of eK8 could represent key molecular mechanisms leading to the formation of metastases, making eK8 a relevant target in colorectal cancer, including KRAS-mutant diseases that are associated with resistance to EGFR inhibition." (PMID 30453567, 2018). "In addition to these assays, the specific phosphorylation of tyrosine 1068 (pY1068) of the epidermal growth factor receptor (EGFR) was quantified upon stimulation with EGF in HCT116 colorectal carcinoma cells." (PMID 29599435, 2018). "Finally, in colorectal carcinoma specimens having an increased IR-A:IR-B ratio the expression of both IR isoforms was higher than that of the epidermal growth factor receptor (EGFR), a clinically validated target in this tumor type." (PMID 30453495, 2018). "EGFR is mainly a predictive factor for the prognosis of post-operative patients with TNM stage I-II colorectal cancer, and nm23 is important for predicting the prognosis of patients with stage III-IV, and EGFR and nm23 could be as predictor of combination." (PMID 27888614, 2017). "Firstly, evidence in the setting of colorectal cancer suggests that oxaliplatin and capecitabine may be suboptimum partners of anti-EGFR antibodies." (PMID 28288572, 2017). "Thus, accumulating evidence suggests that EZH2 is a useful and additional prognostic biomarker for anti-EGFR therapy in patients with colorectal cancer." (PMID 28147317, 2017). "In the current study on patients with colorectal cancer who underwent surgical treatment, we elucidated the association of EZH2 expression, gene mutations, or miR-31 expression in the pathway downstream of EGFR with the efficacy of anti-EGFR therapy." (PMID 28147317, 2017). "With the aim of developing effective preclinical models for testing possible strategies to prevent and/or overcome acquired resistance to EGFR blockade, we have concentrated our efforts on three human colorectal cancer cell lines (SW48, LIM1215 and CACO2) that are sensitive to EGFR inhibition." (PMID 29137301, 2017).
colorectal cancer (continued). "Colorectal cancer is characterized by overexpressing epidermal growth factor receptor (EGFR)." (PMID 29108242, 2017). "MiR-145-5p is also known to target IGF1R in colorectal cancer, as well as EGFR in LAC." (PMID 29137392, 2017). "Usually, IHC EGFR overexpression in tumor tissue implies worst outcome in colorectal cancer." (PMID 28938543, 2017). "The EGFR inhibitor cetuximab is approved for the treatment of colorectal cancer." (PMID 28032592, 2017). "Therefore, we assessed the correlation between RHBDD1 and EGFR in colorectal cancer patient samples." (PMID 28445956, 2017). "In the present study, we investigated the role of RHBDD1 on EGFR in colorectal cancer." (PMID 28445956, 2017). "A tissue microarray was then used to determine RHBDD1 and EGFR expression in colorectal cancer." (PMID 28445956, 2017). "In colorectal cancer, acquired drug resistance to EGFR antibody cetuximab is also being observed to converge upon ERK reactivation that, in turn, could be rationally targeted by further lines of therapy." (PMID 28059068, 2017). "Recall that cetuximab was first approved for colorectal cancer with EGFR expression by IHC in 2004." (PMID 28030802, 2017). "We therefore sequenced these MAP2K1 loci (together with additional mutation hotspots in 34 other genes) in a series of plasma DNA samples collected from 22 colorectal cancer patients who acquired resistance to treatment with EGFR therapies (either Cetuximab or Panitumumab) after an initial response." (PMID 28179366, 2017). "Thus, the predictive value of EGFR IHC testing for cetuximab based therapy in colorectal cancer was found to be questionable." (PMID 29246028, 2017). "In the case of cetuximab and panitumumab, antibodies targeting the epidermal growth factor receptor (EGFR), prospective and retrospective analyses in patients with colorectal cancer (CRC) established the importance of KRAS mutations on sensitivity to these agents." (PMID 28981524, 2017). "In colorectal cancer, increasing evidence exists that the appearance of new KRAS mutations during treatment with agents targeting the EGFR (like cetuximab or panitumumab) may be linked to an acquired resistance to anti-EGFR therapy." (PMID 28549417, 2017). "We further analyzed the association of EZH2 expression with the efficacy of anti-EGFR therapy in patients with colorectal cancer with no mutations in KRAS (codon 61/146), NRAS (codon 12/13/61), or BRAF (codon 600)." (PMID 28147317, 2017). "Thus, our data suggest that EZH2 expression is a useful biomarker for anti-EGFR therapy in patients with colorectal cancer." (PMID 28147317, 2017). "Therefore, we conducted this study for assessing the relationship between EZH2 expression and clinical outcomes in patients with colorectal cancer treated with anti-EGFR therapeutics." (PMID 28147317, 2017). "Cetuximab was initially approved for patients with EGFR overexpressing colorectal cancer." (PMID 28038457, 2017). "Based on these results, we propose that RHBDD1, a member of Rhomboids, may play a role in colorectal cancer by interacting with EGFR." (PMID 28445956, 2017). "By doing this analysis, they demonstrated that primary colorectal cancer and paired metastasis might exhibit difference with respect to EGFR pathway deregulation mechanisms, which may lead to differing response to treatment." (PMID 28097409, 2017). "Moreover, as additional RAS-activating mutations, NRAS mutations have been reported to predict the response in patients with colorectal cancer treated with anti-EGFR therapeutics." (PMID 28147317, 2017). "We and others have previously shown that FOXM1 may play an important role in the response of colorectal cancer cells to anti-EGFR treatment." (PMID 28423516, 2017). "Some study has also demonstrated that anti-EGFR antibody could improve the prognosis of colorectal carcinoma." (PMID 27888614, 2017).
colorectal cancer (continued). "Somatic mutations in KRAS (codons 12, 13) and BRAF (V600E) in colorectal cancer predict poor prognosis and nonresponse to anti-EGFR antibodies." (PMID 27193446, 2016). "Colorectal cancer frequently overexpresses epidermal growth factor receptor (EGFR)." (PMID 27655166, 2016). "Approximately 70% of human colorectal cancers express EGFR protein." (PMID 27927793, 2016). "To evaluate whether Ad-anti-EGFR antibodies can suppress the growth of colorectal cancer cells, we assessed the viability of the colorectal cancer cells infected with AdC68-CTB and Hu5-CTB at different doses." (PMID 27058423, 2016). "FOLFOX was the optimal adjuvant chemotherapy for patients with stage II high-risk and stage III colorectal cancer when TOPIIα was positive or EGFR or P170 was negative." (PMID 27845412, 2016). "For example, in patients with metastatic KRAS wild-type colorectal cancer treated with an anti-EGFR antibody, blood analyses showed that the appearance of KRAS mutants, conferring resistance against anti-EGFR antibodies, preceded progressive disease with up to 10 months." (PMID 27270325, 2016). "Moreover, in advanced colorectal cancer, BRAF mutations are associated with a poor prognosis and possibly resistance to treatment with monoclonal antibodies against EGFR (cetuximab and panitumumab)." (PMID 25902737, 2016). "Moreover, KRAS and NRAS genes mutation limits effectiveness of monoclonal antibodies against EGFR (cetuximab, panitumumab) in colorectal cancer patients." (PMID 25902737, 2016). "DiFi human colorectal cancer cells exhibit unusually high sensitivity to EGFR inhibition: the cells readily undergo apoptosis after treatment with EGFR-blocking monoclonal antibodies or EGFR TKIs." (PMID 27074568, 2016). "Furthermore, clinical EGFR imaging has been performed with 89Zr-cetuximab in advanced colorectal cancer patient." (PMID 27602494, 2016). "Only patients with RAS wild type colorectal cancer are eligible for anti-EGFR treatment." (PMID 27252651, 2016). "Here, we report findings from our study to identify differences in global gene expression between DiFi human colorectal cancer cells; DiFi5, a DiFi subline with acquired resistance to cetuximab; and DiFi-AG, a DiFi subline with acquired resistance to an EGFR tyrosine kinase inhibitor (TKI)." (PMID 27074568, 2016). "This is illustrated in the case of epidermal growth factor receptor (EGFR) in colorectal cancer." (PMID 27814715, 2016). "Anti-EGFR antibodies approved for use in treating human cancers include cetuximab, approved for colorectal and head-and-neck cancers, and panitumumab, approved for colorectal cancers." (PMID 27153091, 2016). "Besides the direct effects that autocrine or paracrine, a recent study has identified exosome-mediated AREG signaling in human breast and colorectal cancer cells, which activates EGFR resulting cell invasion." (PMID 25762634, 2015). "The signaling pathway of epidermal growth factor receptor (EGFR) plays a central role for the biology of colorectal cancer because two monoclonal antibodies directed to EGFR (cetuximab and panitumumab) have become important tools in the management of advanced disease." (PMID 25954997, 2015). "Unlike HER2, positive expression of EGFR is not predictive of response to anti-EGFR therapies, however, overexpression has however been linked to a poorer prognosis in colorectal cancer." (PMID 26149458, 2015). "Interestingly, the critical role of EGFR signaling in the Drosophila intestine is consistent with its role during mammalian gut homeostasis and colorectal cancer development." (PMID 26683696, 2015). "In the case of colorectal cancer, discovery of the role of KRAS mutation in the resistance to the EGFR-targeting antibody (cetuximab or panitumumab) helped to identify a group of patients that can benefit from this kind of treatment (patients with wild-type KRAS)." (PMID 26320181, 2015). "EGFR is a well known activated kinase in many epithelial tumors including colorectal cancer." (PMID 26418718, 2015).
colorectal cancer (continued). "For instance, Dako, the producer of EGFR immunohistochemistry test for patient’s eligibility for Erbitux® in colorectal cancer, reported 70% to 80% over-expression in the initial pivotal trials, while the post-marketing study showed less than 50% over-expression of EGFR." (PMID 26075972, 2015). "On the other hand, EGFR genomic amplification has been suggested to be an alternate and useful biomarker for predicting the therapeutic effect of an anti-EGFR monoclonal antibody in colorectal cancer." (PMID 25154973, 2015). "Mutations in other genes, such as PIK3CA and NRAS may also influence anti-EGFR treatment efficacy in colorectal cancer." (PMID 25568935, 2015). "Furthermore, two pilot studies in advanced colorectal cancer patients with wtKRAS demonstrated emerging KRAS aberrations in cfDNA during treatment with an anti-EGFR therapy." (PMID 25980577, 2015). "Since anti-EGFR targeted therapies such as cetuximab and panitunumab improve tumor response when used in combination with irinotecan in colorectal cancer, it will be interesting to determine the effect of the EGF pathway and of these antibodies on PLCs emergence." (PMID 25565667, 2015). "In colorectal cancer KRAS exons 12 and 13 mutations drive de novo or acquired resistance to anti-EGFR therapy and KRAS and/or BRAF status may change with time between primary and metastatic lesions in colorectal cancer in 17% of patients." (PMID 26474073, 2015). "Over expression of EGFR and Her-2 correlate with invasive colorectal cancer cells in collagen gels." (PMID 26141064, 2015). "Repeatedly, studies on EGFR targeting combined with cytotoxic drugs have been confirmed clinically, the most convincing being the therapeutic success achieved by the cetuximab-irinotecan combination in colorectal cancer." (PMID 26526352, 2015). "EGFR inhibitory therapies are also used against head and neck and colorectal cancer." (PMID 26285137, 2015). "The robust predictive power of such correlations, despite being obtained in retrospective studies, was sufficient to convince both the US Food and Drug Administration and the European Medicines Agency to approve the use of anti-EGFR moAbs only in the subset of KRAS wild-type colorectal cancers." (PMID 24811491, 2014). "After reviewing and summarizing the literature, we found no clear association between the KRAS-LCS6 genotype and overall or progression-free survival among colorectal cancer patients, even after conducting subgroup analysis by stage and anti-EGFR treatment status." (PMID 24890702, 2014). "Additionally, we used siRNA and SecinH3-inhibited ARNO/cytohesins in colorectal cancer cell lines to explore the activity of ARNO and its association with the EGFR and IGF-IR signaling system." (PMID 24618737, 2014). "Epidermal growth factor receptor (EGFR) signaling is commonly activated in colorectal cancer (CRC)." (PMID 24940619, 2014). "In the colorectal cancer setting, preclinical in vitro models of resistance to the anti-EGFR mAbs cetuximab and panitumumab include cell lines showing mutations of the K-Ras gene, most frequently in codon 12 of exon 2, such as SW480, LS174T, HCT116, LoVo cells." (PMID 23992330, 2014). "Building on their previous observation of intrinsic resistance of BRAF mutant colorectal cancers to epidermal growth factor receptor (EGFR) activation, these investigators explored a potential role for EGFR in acquired resistance to BRAF inhibition in BRAF mutant melanoma." (PMID 25031620, 2014). "Emerging data from studies in human embryonic kidney cells and in breast, lung and colorectal cancer cells indicate that the RON kinase interacts with EGFR and may contribute to direct transcriptional regulation." (PMID 25180832, 2014). "Although tyrosine kinase amplification, translocation, or mutations are not common in colorectal cancer, EGFR amplification can be found in a subset of colorectal cancers." (PMID 24968263, 2014).
colorectal cancer (continued). "Herein, we review the latest published literature highlighting the most important genes that may predict resistance to anti-EGFR monoclonal antibodies in colorectal cancer patients." (PMID 25032217, 2014). "For instance, it has been suggested that not all KRAS mutations in colorectal cancer are equally effective in conferring resistance to anti-EGFR antibodies." (PMID 24964744, 2014). "Our findings thus support the notion that DbαEGFR-scTRAIL therapy in combination with apoptosis-sensitizing agents may be promising for the treatment of EGFR-positive colorectal cancers, independently of their KRAS status." (PMID 25198428, 2014). "More recently, we also demonstrated that cross-talks between Sphingosine Kinase 1 (SphK1) and EGFR-dependent signaling pathways could mediate resistance to cetuximab in colorectal cancers." (PMID 23992330, 2014). "Through clinical trials, several groups have observed that colorectal cancer patients without somatic mutations in KRAS benefit from anti-EGFR therapy relative to patients harboring a somatic KRAS mutation 4–8." (PMID 24890702, 2014). "Similarly, our previous studies have shown that blocking cytohesins by SecinH3 or knocking down ARNO by ARNO-siRNA can reduce EGFR activation in the colorectal cancer cell lines HT29." (PMID 24618737, 2014). "Clinical data have shown that colorectal cancers with this mutation do not respond to anti-EGFR therapy." (PMID 25713610, 2014). "Cetuximab and Panitumumab, antibodies against EGFR, are widely used to treat colorectal cancer." (PMID 24618737, 2014). "Whether the strong expression of ARNO in colorectal cancer cells, potentially by enhanced EGFR signaling, contributes to tumor differentiation, survival, proliferation and migration, is yet to be determined." (PMID 23420529, 2013). "Similar mathematical modeling has successfully predicted the dynamics of acquired resistance, including the timing of treatment failure, in colorectal cancer patients treated with the EGFR inhibitor panitumumab, and has led to specific recommendations for combination therapies to treat CML." (PMID 23805382, 2013). "Thus, based on these findings, telmisartan plus combination chemotherapy with anti-EGFR therapy appears to be a better treatment strategy in patients with colorectal cancer, compared to combination chemotherapy with anti-EGFR therapy alone." (PMID 23451083, 2013). "Intriguingly, EGFR also associates and cooperates with STAT5 to target and increase the expression of Aurora A, and its expression is found to be correlated with Aurora A expression in breast and colorectal cancers." (PMID 23936413, 2013). "Expression of EGFR is generally low in melanoma compared to colorectal cancer; however, EGFR overexpression in some melanoma tumors could explain the clinical resistance towards vemurafenib." (PMID 24023633, 2013). "The logic of using a downstream inhibitor to block the consequences of an otherwise undruggable upstream gene defect is thus supported, reinforcing lessons learned from constitutive KRAS-mutant-activated colorectal cancer in which upstream RAS-ERK blockade by EGFR antibodies is ineffective." (PMID 24377088, 2013). "In contrast to these results, a recent guideline does not recommend testing for BRAF mutations in colorectal cancer patients before anti-EGFR treatment." (PMID 24298448, 2013). "A recent study has shown that strong nuclear EGFR expression in colorectal carcinomas is associated with cyclin-D1 but not with gene EGFR amplification." (PMID 23947899, 2013). "For example, anti-epidermal growth factor receptor antibodies should not be administered to colorectal carcinoma patients with KRAS mutations in codons 12 or 13, although improved cost-effectiveness can be demonstrated for the remaining subset of patients." (PMID 23706012, 2013).